FAP (fibroblast activation protein alpha)
Diseases named in the same sentence as FAP in open-access papers (continued):
Sharing a sentence is not in itself a finding about the gene and the disease.
tumor (continued). "conjugated a FAP specific antibody to the nanoparticle ferritin that using photoirradiation allowed local, direct and selective elimination of FAP+ CAFs leading to tumour suppression in mice." (PMID 35479076, 2022). "Heterogeneous expression of FAP among and within tumour lesions correlated with CMS4 heterogeneity (AUROC = 1.00)." (PMID 35296803, 2022). "Multivariate analysis showed that patient age, pathological stage, vascular invasion, pleural invasion, and FAP expression in tumor cells were independent prognostic factors (OS; hazard ratio [HR] = 2.57, 95% confidence interval [CI]: 1.49–4.42, p < 0.001)." (PMID 35818720, 2022). "Taken together, our results suggest that tumor cell–derived FGFBP1 induces FAPα expression in HSCs and promotes vessel co-option." (PMID 35951441, 2022). "Depletion of FAP disrupts the immunosuppressive environment around tumor tissues and relieves therapy resistance." (PMID 35326556, 2022). "Tumor uptake of 177Lu-FAP-2286 at the 3-h timepoint was 21.1 %ID/g and demonstrated durable retention with 16.4 %ID/g 72 h later." (PMID 35608703, 2022). "Subsequently, [68Ga]-labeled FAPI provided PET/CT images with high tumor-to-background ratios (TBRs) in a wide variety of cancer patients, suggesting high potential for FAP-targeted diagnosis and possibly targeted, radioligand therapies in the future." (PMID 35202189, 2022). "As such, FAP has been used as a co-target to deliver the T cell co-stimulatory 4-1BB ligand selectively to the tumour thereby circumventing systemic side effects of 4-1BB ligand such as cytokine release syndrome." (PMID 35479076, 2022). "Our results on protein expression using western blot assay also showed an increase in COL10A1, BGN, and FAP proteins in tumor tissue compared with adjacent normal tissue, consistent with staging." (PMID 35328635, 2022). "Administration of a DNA-based FAP vaccine enabled killing of CAF by tumor-infiltrating CD8, thus facilitating ECM modification, ultimately leading to improved efficacy of chemotherapeutics in multi-drug resistant murine colon and breast carcinoma." (PMID 35892828, 2022). "FAPα, a cell surface protein expressed on activated CAFs in many tumour types, is considered to be a crucial contributor to the immunosuppressive TME and is associated with a poor prognosis." (PMID 36046842, 2022). "Its expression was shown to facilitate the ability of macrophages to migrate through the collagen networks found in the dermis and in the tumor microenvironment, similar to the mechanism demonstrated for FAP-expressing (FAP+) fibroblasts." (PMID 35719937, 2022). "We first detected FAP on NB- and myeloid-derived suppressor cells (MDCS) in tumor tissue and showed a tumor-cell-dependent enhancement in FAP expression by fibroblasts." (PMID 36230765, 2022). "The authors first performed pre-clinical studies in murine tumour models expressing FAP which showed better uptake 1 hour post injection when compared to the developed by the University of Heidelberg FAPI-46 ligand, but with similar washout characteristics." (PMID 36182995, 2022). "More recently, a synthetic consensus sequence approach to provide MHC class II help was used to develop a FAP DNA vaccine, which was shown to synergize with other tumor antigen-specific DNA vaccines to enhance CD8+ and CD4+ antitumor immunity." (PMID 36338519, 2022). "FAP is an attractive cell surface target for radiopharmaceutical development given its tumor-restricted expression profile." (PMID 35608703, 2022). "We found that although primary B16-FAP tumor volumes were similar in vehicle- and FAP-IL2v-treated mice, the tumor uptake of [68Ga]Ga-DOTA-Siglec-9 was increased in FAP-IL2v-treated mice." (PMID 35874707, 2022). "Bevacizumab treatment induced FAPα expression in HSCs and promoted tumor cell EMT and MDSC recruitment, which in turn significantly facilitated vessel co-option." (PMID 35951441, 2022).
tumor (continued). "Although the application of FAP-IL-2 has been reported to stimulate effector cells in the periphery as well, the fusion of IL-2v to the anti-FAP Ab was performed to preferentially transport an additional stimulating agent (IL-2v) into the tumor tissue." (PMID 36230765, 2022). "Analysis of The Cancer Genome Atlas (TCGA) database showed that FAP mRNA was highly expressed in most human tumor tissues." (PMID 35186170, 2022). "These prodrugs remain inactive when systemically delivered and are proteolytically activated upon cleavage by FAP, which is expressed on CAFs in the tumor." (PMID 36010899, 2022). "Fibroblast activation protein (FAP) is a membrane-anchored peptidase expressed by CAFs at the stromal level of various tumor entities and contributes to progression and a worse prognosis." (PMID 35745648, 2022). "A total of 280 patients (81.4%) had low FAP expression, and 64 patients (18.6%) had high FAP expression in tumor cells." (PMID 35818720, 2022). "Univariate analysis revealed that sex, patient age, smoking, pathological stage, histological subtype, lymphocytic invasion, vascular invasion, pleural invasion, FAP expression in tumor cells, and FAP expression in CAFs were significant prognostic factors." (PMID 35818720, 2022). "[99mTc]Tc-iFAP boronic acid showed stability in human serum, specific recognition of FAP, fast kidney elimination, and high tumor uptake (7.05% ID/g)." (PMID 35631416, 2022). "FAP levels were validated by immunohistochemistry in human tumor samples on tissue microarrays (TMA) of 19 cancers (n = 1829 cores)." (PMID 35608703, 2022). "FAP-targeted molecular imaging agents, including the FAP inhibitors (FAPIs) 04 and 46, have shown promising results in tumor diagnosis." (PMID 34556528, 2022). "For example, a humanized version of monoclonal antibody F19, sibrotuzumab has been developed to target the cell surface bound FAP on tumor stromal fibroblasts and explored for its anti-tumor response." (PMID 35222418, 2022). "The expression of FAP in the tumor tissues of GC patients is different in StromalScore, ImmuneScore, and ESTIMATEScore, and the higher the FAP expression in tumor tissues of GC patients, the higher the TME score." (PMID 36010886, 2022). "In vivo depletion of FAP-positive stromal cells inhibits tumor growth by decreasing cancer support, increasing antitumor immunity, and limiting stromal barrier effects." (PMID 34740953, 2022). "Malignant cells drive the generation of desmoplastic and immunosuppressive tumor microenvironments, and emerging evidence indicates that FAP is aberrantly expressed in CAFs, chimeric antigen receptor T (CAR-T) cells, and a subset of M2 macrophages." (PMID 36263225, 2022). "For this technique, a specimen of the tumor is characterized in vitro by labelling a discriminative (colored) molecule to a specific target, in this case FAP." (PMID 36428657, 2022). "For most tumor specimens examined, FAP expression was restricted to the CAFs in the stromal cell compartment of the tumor." (PMID 35608703, 2022). "When FAP is overexpressed in GC patients, it can increase the malignancy of the tumor, promote the proliferation, migration, invasion, and apoptosis inhibition of SGC7901 cells, and induce apoptosis of GES1 cells in vitro." (PMID 36010886, 2022). "Although FAP antibodies have shown limited response in tumor therapy, small molecules targeting FAP have attracted increasing attention in the area of tumor theranostics." (PMID 35198057, 2022). "For example, FAP causes rapid hypoxic necrosis of both cancer and stromal cells in dependence on IFN γ and TNFα to facilitate anti-tumor T cell infiltration and function, bringing benefits in transplantable models of NSCLC and PDAC." (PMID 35488263, 2022). "Two novel 18F-labeled PSMA-FAP heterodimeric radiotracers containing both PSMA and FAP pharmacophores were designed and synthesized for dual PSMA and FAP-targeted tumor imaging." (PMID 35337180, 2022).
tumor (continued). "For instance, bone marrow (BM)-derived human MSCs exposed to tumour-conditioned medium differentiate and express myofibroblast markers αSMA and fibroblast activation protein-alpha (FAPα)." (PMID 36555218, 2022). "The tumor accumulations were highly FAP-selective and resulted in remarkable inhibition of PDX tumor growth, with negligible side effects." (PMID 34593598, 2022). "In preclinical models, radiolabeled FAP-2286 demonstrated high tumor uptake and retention, as well as potent efficacy in FAP-positive tumors." (PMID 35608703, 2022). "FAPα expression in tumor stroma is observed in 90% of human cancers of epithelial origin and has been described to induce tumor progression and chemoresistance." (PMID 35740561, 2022). "Rationale: Fibroblast activation protein (FAP) targeted molecular imaging radiotracers have shown promising preclinical and clinical results in tumor diagnosis." (PMID 34987657, 2022). "A cohort of surgical patients representing 10 of those cancer types was then tested to determine the correlation between 68Ga-FAPi-46 PET biodistribution and FAP immunohistochemistry expression in excised tumor tissue." (PMID 34740953, 2022). "We noted that FAP expression was also high in a subset of CMS1 tumours, a subtype largely consisting of tumours with high levels of microsatellite instability (MSI-H)." (PMID 35296803, 2022). "And FAP plays a seemingly ever-increasing role in tumor development, especially in relation to tumor initiation and metastasis." (PMID 36401232, 2022). "In our tumor model, we detected FAP only by tumor-infiltrating CD11b-positive leukocytes, especially by the two MDCS populations, M- and PMN-MDSC." (PMID 36230765, 2022). "FAP is overexpressed by CAFs from various tumor entities, making it a promising biomarker and target for many medical interventions." (PMID 35745648, 2022). "As expected, the immunotherapy with DB showed, in the resistant tumor model, similar tumor growth compared to the monotherapy controls with FAP-IL-2 or IL-2." (PMID 36230765, 2022). "The deletion of FAP+CAF slows tumor growth, whereas the suppression of α-smooth muscle actin (SMA)-expressing CAFs mediates immunosuppression and decreases survival." (PMID 36233024, 2022). "Accordingly, the observed manyfold difference of uptake between FAP+/FAP− tumor lines can be solely attributed to specific tracer binding." (PMID 34957527, 2022). "The status of FAP expression in tumor cells and CAFs was correlated with clinicopathological background, molecular features, and patient outcomes." (PMID 35818720, 2022). "In summary, we presented the design and synthesis of novel FAPα activatable pro-photosensitizer FAP-MB-X with different N-terminal blocked structures for tumor-selective NIR fluorescence imaging and high-efficiency PDT." (PMID 35664057, 2022). "The longer tumor retention of FAP-2286 as compared to FAPI-46 resulted in 12- and 9-fold higher TIAC and absorbed dose delivered to the tumors, respectively, which ultimately lead to greater tumor inhibition." (PMID 35608703, 2022). "The anti-EGFR or anti-FAP bispecific antibody-targeted liposomal irinotecan (BS−LipoIRI) were examined for both in vitro and in vivo specific targeting ability and tumor growth inhibition effect." (PMID 35745775, 2022). "In line with expectations, it has been observed that the tumor progression promoting and MDSC recruiting effects of FAP+ CAFs are abolished in Ccr2-deficient mice." (PMID 36263225, 2022). "In particular, 68Ga-FAPI-46 was reported to have a high specificity and affinity for FAP-expressing cells, a fast and high accumulation in tumor lesions/injuries together with a fast body clearance when investigated in vivo." (PMID 35163938, 2022). "Based on the SPECT imaging observations, 177Lu-FAP-2286 antitumor efficacy was evaluated as a single dose of 30 or 60 MBq in HEK-FAP tumor bearing mice." (PMID 35608703, 2022).
tumor (continued). "To enhance tumor uptake and retention, we designed and developed bi-specific heterodimeric radiotracers targeting both FAP and αvβ3, [68Ga]Ga-FAPI-RGD." (PMID 36276644, 2022). "Gain- or loss-of-function experiments revealed that the bevacizumab-resistant tumor cell–derived FGFBP1 induced FAPα expression by enhancing the paracrine FGF2/FGFR1/ERK1/-2/EGR1 signaling pathway in HSCs." (PMID 35951441, 2022). "Immunofluorescence staining of B16-FAP tumors revealed that the expression of VAP-1 on tumor vasculature was similar in FAP-IL2v-treated and vehicle-treated groups." (PMID 35874707, 2022). "We demonstrate that the tumor-specific FAP+ fibroblasts and SPP1+ macrophages were positively correlated in 14 independent CRC cohorts containing 2550 samples and validate their close localization by immuno-fluorescent staining and spatial transcriptomics." (PMID 35365629, 2022). "The 99mTc-iFAP, designed and synthesized for this research, shows suitable properties as a new FAP inhibitor radioligand based on the 99mTc-HYNIC-D-alanine-boroPro structure for SPECT tumor microenvironment imaging." (PMID 35011496, 2022). "Depletion of FAP+ CAFs by antibody-drug conjugate (ADC) OMTX705 combined with gemcitabine achieved durable tumor regression for more than 90 days in a PDAC PDX model." (PMID 36230914, 2022). "Since we previously showed a tumor-promoting role of CD11b-positive cells in NB, we assessed first FAP expression by this cell population (GD2-/CD45+/CD11b+)." (PMID 36230765, 2022). "Compared with normal fibroblasts, cancer-associated fibroblasts express increased markers, such as FAP, PDGFRα, and αSMA, which have been used as biomarkers to isolate CAF population from the tumor tissue." (PMID 35155261, 2022). "On day 19 p.i., a single dose of 30 or 60 MBq 177Lu-FAP-2286 demonstrated significant tumor growth inhibition as the treatment-to-control ratio was 45% for both doses (P < 0.01)." (PMID 35608703, 2022). "Recent studies support this claim; FAP-IL2v used in combination with another drug mediates anti-tumor activity." (PMID 35874707, 2022). "In the univariate analysis for OS, sex, tumor depth, lymph node status, and high FAP expression were statistically significant prognostic factors." (PMID 36418422, 2022). "The longer tumor retention of FAP-2286, on the other hand, allows the use of therapeutically effective longer-lived radionuclides for therapy (including 177Lu and 225Ac)." (PMID 34168013, 2022). "68Ga-labeled FAP inhibitors based on the cyanopyrrolidine structure (FAPI) are currently used for the detection of the tumor microenvironment by PET imaging." (PMID 35011496, 2022). "Multivariate analysis showed that patient age, pathological stage, vascular invasion, pleural invasion, and FAP expression in tumor cells were independent predictive factors for recurrence (RFS; HR = 2.13, 95% CI: 1.38–3.29, p < 0.001)." (PMID 35818720, 2022). "CAFs mediate tumorigenesis and metastasis by secreting tumor cell stimulating factors such as TGFβ as well as through the action of fibroblast activation protein (FAP), thereby facilitating tumor cell migration." (PMID 34854061, 2022). "Patients with high tumor FAP expression had proportionally higher Gleason 9 scores at RP (9/21 or 43% vs. 58/187 or 31%)." (PMID 35052475, 2022). "In PAAD, TAMs in the tumor stroma also secretes FAP, shifting their phenotype to an immunosuppressive M2 macrophage type, suppressing the adaptive immune response, and promoting a positive feedback loop in PAAD progression." (PMID 36263225, 2022). "A single dose of vehicle, natLu-FAP-2286, or 177Lu-FAP-2286 at 30 or 60 MBq was administered to Sarc4809 tumor bearing mice." (PMID 35608703, 2022). "NPC patients who developed metastasis had significantly higher levels of active YAP1 and FAPα in their tumor stroma, which was further correlated with tumor fibrosis and poorer metastasis-free survival." (PMID 35986369, 2022).
tumor (continued). "Despite higher persistence of 4-1BB/CD3ζ CAR-T cells, statistically significant tumor control in vivo was only obtained when combining FAP-ΔCD28/CD3ζ CAR-T cells with the immune checkpoint PD-1 inhibitor antibodies." (PMID 35211124, 2022). "Several studies have shown that the radiotracer [68 Ga]Ga-FAPI binds to fibroblast-activation-protein (FAP) in fibroblasts of tumor tissue." (PMID 34988624, 2022). "The development of fibroblast activation protein (FAP) imaging has represented a major advance in oncological PET imaging given that it can be used to image many tumor types." (PMID 35626272, 2022). "Secondly, compared with FAPI-02, FAPI-04 showed higher affinity to FAP, slower excretion in vitro and a higher standardized uptake value in tumor-bearing mice." (PMID 34987657, 2022). "Since FAP expression in normal tissue is limited, it has been identified as a pan-tumor target for the potential treatment of cancer." (PMID 34168013, 2022). "The past few years have witnessed an expansion of research on FAP-targeted molecular imaging in tumor diagnosis." (PMID 34556528, 2022). "It has been demonstrated that altered tumor microenvironment or inflammation induces FAP expression through stimulation of cytokines such as TGF-β1 and TNF-α, chemical substances, or physical stimulants." (PMID 35222418, 2022). "A FAP vaccine using a modified vaccinia Ankara vector combined with cyclophosphamide also significantly enhanced anti-tumor immune response decreased Tregs infiltration, and prolonged the survival of 4T1 tumor-bearing mice." (PMID 36338519, 2022). "Briefly, high FAP expression of both tumor cells and CAFs was frequently found in the patients with solid predominant adenocarcinoma (53.8% in tumor cells and 61.5% in CAFs, respectively) than other subtypes of adenocarcinoma." (PMID 35818720, 2022). "Depletion of fibroblast activation protein-positive (FAP+) stroma cells enables immunological control of tumor growth by IFNγ and TNFα." (PMID 36230914, 2022). "CAFs and normal fibroblasts (NFs) isolated from primary cultures of four tumor masses and skin were validated by flow cytometry using antibodies against fibroblast activation protein (FAP) and CD90." (PMID 36514170, 2022). "The tumor half-life of FAP-2286 is much longer than that of FAPI-02 or FAPI-04 but less than that of 177Lu-PSMA, 177Lu-DOTATOC, or 177Lu-DOTATATE." (PMID 34168013, 2022). "The biodistribution of 111In-FAP-2286 was evaluated in vivo by SPECT imaging following a single dose of 30 MBq in HEK-FAP tumor bearing mice." (PMID 35608703, 2022). "T cells redirected by anti-FAP chimeric antigen receptor (CAR) impair tumor growth in lung cancer models." (PMID 36230914, 2022). "Favorable radiochemical properties, rapid clearance from organs and soft tissues, and intense tumor uptake validate 68Ga-OncoFAP as a powerful alternative to currently available FAP tracers." (PMID 34957527, 2022). "Simultaneous binding of anti-FAP to CAFs and 4-1BBL to T cells resulted in the clustering and activation of T and NK cells at the tumour site, thereby leading to potent antitumour activity in mice xenograft models." (PMID 35158891, 2022). "For example, in pancreatic ductal carcinoma, CXCL12 from FAP+ CAFs can wrap tumor cells and inhibit the accumulation of T cells in tumor sites." (PMID 35681617, 2022). "Considering the vital role in tumor survival and cancer growth, cancer-associated fibroblast–targeted diagnosis and therapy via the biomarker FAP have become an attractive strategy for tumor treatment." (PMID 34593598, 2022). "Further work using mouse tumor models with FAP-positive CAFs infiltration is warranted, and model development studies are on-going to recapitulate CAFs recruitment and maintenance in mice." (PMID 35608703, 2022).